RNF112 (ring finger protein 112)
Description:
E3 ubiquitin-protein ligase that plays an important role in neuronal differentiation, including neurogenesis and gliogenesis, during brain development. During embryonic development initiates neuronal differentiation by inducing cell cycle arrest at the G0/G1 phase through up-regulation of cell-cycle regulatory proteins. Plays a role not only in the fetal period during the development of the nervous system, but also in the adult brain, where it is involved in the maintenance of neural functions and protection of the nervous tissue cells from oxidative stress-induced damage. Exhibits GTPase and E3 ubiquitin-protein ligase activities. Regulates dendritic spine density and synaptic neurotransmission; its ability to hydrolyze GTP is involved in the maintenance of dendritic spine density (By similarity).
Synonyms: BFP; ZNF179
Tractability: Antibody: UniProt places it where antibodies can reach, with medium confidence; UniProt predicts a signal peptide or a membrane-spanning region. PROTAC: UniProt records ubiquitination sites on it.
Gene: Protein-coding gene on chromosome 17 (19,410,959 to 19,417,281, forward strand). Ensembl gene ENSG00000128482.
Subcellular location: Membrane; Cytoplasm; Nucleus; Nucleus, nuclear body; Nucleus, nucleoplasm; Endosome; Cytoplasmic vesicle, secretory vesicle, synaptic vesicle; Postsynaptic density; Perikaryon; Cell projection, neuron projection
Subcellular location (Human Protein Atlas): Nuclear speckles
Gene Ontology:
Molecular function: protein binding; GTP binding; GTPase activity; ubiquitin protein ligase activity; zinc ion binding; metal ion binding
Biological process: neuron differentiation; regulation of cell cycle; embryonic brain development; endoplasmic reticulum organization; protein autoubiquitination; protein homooligomerization; response to hydroperoxide; protein ubiquitination
Cellular component: cell body; cytoplasm; endosome; membrane; nuclear body; nucleoplasm; nucleus; perikaryon; postsynaptic density; synaptic vesicle; neuron projection
Genetic constraint (gnomAD): Loss-of-function variants: 34 observed, 60.94 expected, observed/expected ratio (o/e) 0.56, 90% interval 0.42 to 0.74. The upper end of that interval is the gene's LOEUF score, 0.74, which puts it in group 3 of 6, group 1 being the genes least tolerant of losing a copy. Missense variants: 734 observed, 844.2 expected, observed/expected ratio (o/e) 0.87, 90% interval 0.82 to 0.92. Synonymous variants: 345 observed, 341.86 expected, observed/expected ratio (o/e) 1.01, 90% interval 0.92 to 1.1.
Homologues: Orthologues: chimpanzee RNF112 (99% identical), macaque RNF112 (98% identical), guinea pig RNF112 (90% identical), mouse Rnf112 (88% identical), pig RNF112 (87% identical), rat Rnf112 (86% identical), dog RNF112 (82% identical), tropical clawed frog rnf112 (32% identical), tropical clawed frog rnf112 (26% identical), tropical clawed frog rnf112.2 (24% identical), Drosophila melanogaster atl (16% identical). Paralogues in human: ATL3 (18% identical), ATL2 (18% identical), ATL1 (18% identical), GBP6 (13% identical), GBP7 (13% identical), GBP2 (12% identical), GBP4 (12% identical), GBP5 (12% identical), GBP1 (11% identical), GBP3 (11% identical).
Diseases named in the same sentence as RNF112 in open-access papers:
RNF112 is named in the same sentence as 17 diseases in open-access papers, as found by Europe PMC text mining. Sharing a sentence is not in itself a finding about the gene and the disease. The quoted sentences say what the papers report.
amyotrophic lateral sclerosis (3 papers, 2013 to 2025). Amyotrophic lateral sclerosis (ALS) is a neurodegenerative disease characterized by progressive muscular paralysis reflecting degeneration of motor neurons in the primary motor cortex, corticospinal tracts, brainstem and spinal cord. "In mouse models of Huntington’s disease and amyotrophic lateral sclerosis (ALS), RNF112 is downregulated in the motor neurons." (PMID 40198702, 2025).
gastric cancer (2 papers, 2023 to 2025). A primary or metastatic malignant neoplasm involving the stomach. "FOXM1 and RNF112 are both associated with the proliferation and invasion signaling pathways in gastric cancer." (PMID 37288663, 2023). "Interestingly, RNF112 was most negatively associated with FOXM1 in gastric cancer tissues." (PMID 37288663, 2023). "Taken together, our results demonstrate that RNF112, a neurodevelopment-related protein, plays a promising antitumor role in gastric cancer by inducing the ubiquitination and degradation of oncoprotein FOXM1." (PMID 37288663, 2023). "Of note, mechanism study revealed that RNF112 directly ubiquitinates FOXM1 in gastric cancer, resulting in a decreased FOXM1 transcriptional network and suppressing the proliferation and invasion of gastric cancer." (PMID 37288663, 2023). "Because of the carcinogenic roles of FOXM1 in gastric cancer, ectopic expression of RNF112 markedly inhibited the proliferation and invasion of MGC803 and BGC823 cells." (PMID 37288663, 2023). "Further studies demonstrate that RNF112 plays a tumor-suppressor role by targeting FOXM1, whose expression is negatively associated with that of FOXM1 in gastric cancer." (PMID 37288663, 2023). "Here, we found that besides the brain, RNF112 is expressed in gastric tissues according to TCGA data and gastric cancer TMAs." (PMID 37288663, 2023). "RNF112 suppresses the malignancies of gastric cancer cells by suppressing the FOXM1 transcriptional network in vitro." (PMID 37288663, 2023). "To assess the potential significance of RNF112 in gastric cancer, we examined the downstream mRNA networks of RNF112 and FOXM1 by RNA-Seq." (PMID 37288663, 2023). "We demonstrate that RNF112 abundance is significantly inhibited in gastric cancer tissues." (PMID 37288663, 2023). "RNF112-inhibited FOXM1 expression suppresses gastric cancer malignant behaviors in vivo." (PMID 37288663, 2023). "Moreover, RNF112 exhibits low expression in gastric cancer tissues, and patients with low RNF112 expression had a poor prognosis." (PMID 37288663, 2023). "Interestingly, among these E3 ubiquitin ligases, RNF112 was decreased most dramatically in gastric cancer settings." (PMID 37288663, 2023). "FOXM1 exhibits inverse correlation with RNF112 in gastric cancer tissues." (PMID 37288663, 2023). "Taken together, these findings suggest that the RNF112/FOXM1 axis could potentially serve as a diagnostic and therapeutic biomarker for gastric cancer." (PMID 37288663, 2023). "Notably, a marked inverse association between RNF112 and FOXM1 was noticed in gastric cancer compared with the other 32 tumor settings, indicating the RNF112/FOXM1 axis is relatively more important in gastric cancer." (PMID 37288663, 2023). "Furthermore, RNF112 exhibited the strongest negative association with FOXM1 in 5 independent gastric cancer cohorts derived from the NCBI Gene Expression Omnibus (GEO) and TCGA." (PMID 37288663, 2023). "Interestingly, patients with gastric cancer with high FOXM1/low RNF112 displayed the shortest survival, indicating that the combination of the 2 indices could predict the survival of patients more sensitively." (PMID 37288663, 2023). "As a result, RNF112-Mut was unable to interfere with FOXM1 downstream genes and almost lost its tumor suppressor roles in gastric cancer." (PMID 37288663, 2023). "The distribution of the patients with gastric cancer based on FOXM1 and RNF112 expression was revealed by t-distributed stochastic neighbor embedding analysis." (PMID 37288663, 2023). "Thus, the RNF112/FOXM1 axis not only could be considered a potential biomarker for predicting patients’ prognosis but also could be developed as a therapeutic target to combat gastric cancer." (PMID 37288663, 2023). "Although several E3 ligases have been identified, here, via ON-TARGETplus siRNA library–based approaches, an E3 ubiquitin ligase, RNF112, was identified as promoting the ubiquitination and degradation of FOXM1 in gastric cancer." (PMID 37288663, 2023).
gastric cancer (continued). "In the meantime, RNF112 and STUB1 expression was significantly suppressed in gastric cancer compared with adjacent paracancer tissues revealed by TCGA data." (PMID 37288663, 2023). "Furthermore, RNF112 was proven to serve as a tumor repressor by mediating the proteasomal degradation of FOXM1 and inhibiting its transcriptional network in gastric cancer." (PMID 37288663, 2023). "Altogether, we demonstrate that RNF112 suppresses gastric cancer progression by ubiquitinating FOXM1 and highlight the RNF112/FOXM1 axis serves as both prognosis biomarker and therapeutic target in gastric cancer." (PMID 37288663, 2023). "To echo this finding, we observed that administration of RCM-1 largely attenuated intact but not RNF112-deleted gastric cancer growth in a xenograft mouse model." (PMID 37288663, 2023). "RNF112 suppresses FOXM1 protein expression and stability in gastric cancer." (PMID 37288663, 2023).
glioblastoma (2 papers, 2017 to 2025). The most malignant astrocytic tumor (WHO grade IV). "Studies have demonstrated a significant downregulation of RNF112 in malignant glioblastoma multiforme, with low RNF112 mRNA levels strongly correlated with a negative prognosis." (PMID 40178292, 2025).
bladder cancer (1 paper, 2025). "To further investigate the mechanism by which RNF112 regulates c‐Myc, we performed immunoprecipitation‐mass spectrometry (IP‐MS) analysis after overexpressing Flag‐RNF112 in bladder cancer T24 cells." (PMID 40178292, 2025). "The E3 ubiquitin ligase RNF112 is significantly downregulated in bladder cancer (BLCA) and is correlated with disease progression." (PMID 40178292, 2025). "RNF112, an E3 ubiquitin ligase, is markedly reduced in bladder cancer (BLCA)." (PMID 40178292, 2025).
colorectal cancer (1 paper, 2023). A primary or metastatic malignant neoplasm that affects the colon or rectum. "In 5 independent gastric and colorectal cancer cohorts obtained from GEO and TCGA, RNF112 was negatively correlated with FOXM1 downstream genes, including CKS1, CCNB1, SKP2, and FN1." (PMID 37288663, 2023).
tumor (6 papers, 2011 to 2025). "H&E staining and Ki67 staining of subcutaneous tumor tissues revealed a significant increase in heterogeneity and proliferative capacity in the RNF112+c‐Myc group compared with the RNF112 group." (PMID 40178292, 2025). "H&E staining and Ki67 staining of subcutaneous tumor tissues revealed that RNF112 inhibited the proliferative capacity of BLCA cells." (PMID 40178292, 2025). "H&E staining of the lymph nodes confirmed that more extensive tumor metastasis occurred in the lymph nodes of the RNF112+c‐Myc group than in those of the RNF112 group." (PMID 40178292, 2025). "Compared with those in the RNF112 group, the tumor volume and weight in the RNF112+c‐Myc group were significantly greater." (PMID 40178292, 2025). "IHC staining revealed that xenograft tumor tissues from the RNF112‐overexpressing group presented lower levels of c‐Myc protein than did those from the control group." (PMID 40178292, 2025). "The subcutaneous xenograft model confirmed a significant reduction in tumor volume and weight in the RNF112 group compared with those in the control group." (PMID 40178292, 2025). "Oil Red O staining revealed that xenograft tumor tissues in the RNF112‐overexpressing group presented lower levels of lipid droplets than did those in the control group." (PMID 40178292, 2025). "The results showed that the tumor-promoting effect of RNF112 depletion was dramatically rescued via ectopic RNF112 expression in RNF112 KO cells." (PMID 37288663, 2023). "We observed that RNF112 noticeably decreased tumor growth and weight in vivo, coupled with the decreased FOXM1 and its downstream genes’ expression." (PMID 37288663, 2023). "In addition, in the footpad‐popliteal lymph node metastasis model, the RNF112‐overexpressing group had fewer lymph nodes and fewer tumor metastases, suggesting that RNF112 inhibits lymph node metastasis in BLCA in vivo." (PMID 40178292, 2025). "Nonetheless, there is limited understanding of the potential effect of RNF112 on tumor progression." (PMID 37288663, 2023). "The role of RNF112 in vivo was then studied using xenograft tumor models." (PMID 37288663, 2023). "Likewise, RNF112 depletion readily increased tumor growth and weight, coupled with elevated expression of FOXM1 and its downstream target genes, as well as that of Ki67 and PCNA in vivo." (PMID 37288663, 2023). "According to the UALCAN dataset, RNF112 mRNA expression was downregulated in BLCA tissues with different lymph node metastasis statuses, tumor stages, and molecular subtypes compared with normal tissues." (PMID 40178292, 2025). "In addition, we performed Oil Red O staining and IHC staining for ACLY in tumor tissue from the subcutaneous xenograft model and revealed significantly reduced lipid droplet content and ACLY expression in the xenograft tissues of the RNF112 group." (PMID 40178292, 2025).
cancer (4 papers, 2017 to 2025). A tumor composed of atypical neoplastic, often pleomorphic cells that invade other tissues. "The TIMER2.0 and GEPIA datasets revealed that RNF112 mRNA was significantly downregulated in most cancers, including BLCA." (PMID 40178292, 2025). "Multicolor immunofluorescence analysis revealed that FOXM1 was expressed more highly in cancer tissues and was accompanied by lower RNF112 expression." (PMID 37288663, 2023). "For instance, UHRF1 and RNF112 had higher methylation across some cancer types than normal cells." (PMID 40591126, 2025). "Because FOXM1 could be transcriptionally upregulated by itself, we further analyzed the correlation between RNF112 and FOXM1 in The Cancer Gene Atlas (TCGA) database." (PMID 37288663, 2023). "Notably, in cancer tissues, prominent colocalization between FOXM1 and RNF112 was observed." (PMID 37288663, 2023).
RNF112 also shares sentences with these, for which no sentence is quoted: Huntington disease (2 papers); neurodegenerative disease (2); astrocytomas (1); frontotemporal lobar degeneration (1); glioma (1); neuropathy (1); Pituitary adenoma (1); proteinopathies (1); Smith-Magenis syndrome (1); Stroke (1).